ACSL4 (acyl-CoA synthetase long chain family member 4)
Diseases named in the same sentence as ACSL4 in open-access papers (continued):
Sharing a sentence is not in itself a finding about the gene and the disease.
breast cancer (continued). "Long-chain acyl-CoA synthetase 4 (ACSL4), a critical factor which links arachidonic acid (AA) and adrenic acid (AdA) to phosphatidylethanolamine (PE) was shown to be highly expressed in basal-type breast cancer cells and regulated ferroptosis sensitivity." (PMID 36130940, 2022). "RT-PCR detections confirmed that only 2 of the 19 (10.5%) ER positive breast cancer cell lines existed ACSL4 mRNA expression, and ACSL4 mRNA was broadly expressed in 20 of 31 (64.5%) ER negative cell lines." (PMID 35910359, 2022). "In addition, the protein expression pattern of ACSL4 was analyzed by UALCAN database, and it was found that ACSL4 was highly expressed in colorectal cancer and low in breast cancer." (PMID 35126480, 2022). "In breast cancer cell panels, which have diverse expression levels of ACSL4, the level of GPX4 is inversely proportional to that of ACSL4 and cell viability, and is correlated with the effect of ACSL4 in the esterification of AA and AdA into phosphatidylethanolamines (PE)." (PMID 34249928, 2021). "Given that ACSL4 has been found necessary for ferroptosis in breast cancer cells, we also report our findings regarding the subcellular targeting of endogenously expressed ACSL3 and ACSL4 in MCF7 breast cancer cells." (PMID 29450800, 2018). "The expression of Acyl-CoA synthetase 4 (ACSL4), an enzyme participating in arachidonic acid metabolism, drives the hyperactivation of the PI3K-Akt-mTOR pathway in in vitro transfection experiments in breast cancer cells." (PMID 27765921, 2017). "Since normal mammary epithelium is predominantly receptor-negative, ACSL4 expression is positive for normal compared with most (i.e. receptor-positive) breast cancer tissue." (PMID 24155918, 2013). "We also aim to determine whether a combinatorial inhibition of the ACSL4-LOX-COX-2 pathway affects tumor growth in vivo using a xenograft model based on MDA-MB-231 cells, a highly aggressive breast cancer cell line naturally overexpressing ACSL4." (PMID 22808264, 2012). "We previously demonstrated that the sole transfection of MCF-7 cells, a model of non-aggressive breast cancer cells, with ACSL4 cDNA, transforms those cells into a highly aggressive phenotype." (PMID 22808264, 2012). "One study found that ACSL4, a key inducer of ferroptosis, enhanced the ferroptosis sensitivity of breast cancer cells in an AA-dependent manner, and overexpression of ACSL4 was positively related to the sensitivity to ferroptosis induced by RSL3 in breast cancer cells." (PMID 36243728, 2022). "In addition, silencing ACSL4 expression only partly inhibits Polyphyllin III induced ferroptosis, indicating that there are additional pathways participating in the tumor suppression effect of Polyphyllin III on breast cancer cells." (PMID 34040532, 2021). "Similarly, when HER2-positive, ACSL4-negative, SKBr3 breast cancer cells were induced to express ACSL4, the proliferation rate increased and the apoptotic effect of lapatinib was reduced." (PMID 24155918, 2013). "ACSL4 expression in steroid hormone/HER2 receptor negative breast cancer cell lines." (PMID 24155918, 2013). "Breast cancer is not the only cancer demonstrated to differentially express ACSL4." (PMID 24155918, 2013). "Thus, ACSL4 and ZEB2 could specifically be used as prognostic markers for breast cancer, and this axes hold promise as a new metabolic therapeutic target for highly invasive breast cancer." (PMID 38078907, 2023). "It is important to investigate how both classical pathways, such as GPX4/ACSL4 ferroptosis signaling, and non-classical pathways, like GPX4-independent ferroptosis, influence breast cancer progression, invasion, and metastasis." (PMID 39664391, 2024). "In breast cancer cells with HER2 positive and ACSL4 negative, the up regulation of ACSL4 will increase the proliferation rate and lead to drug resistance of lapatinib." (PMID 37305043, 2023).
breast cancer (continued). "Quadruple-negative breast cancer tissues, on the other hand, have higher expression of ACSL4 than their healthy counterparts, whereas ER- breast cancer overexpresses ACSL1, ACSL3, ACSL4 and ACSL4." (PMID 35448537, 2022). "In order to further evaluate the effect of ACSL4 expression on the mTOR pathway observed with the MCF-7 Tet-Off/ACSL4 cells, we next produced an ACSL4-overexpressing system using a different non-aggressive breast cancer cell line, i.e. T47D cells." (PMID 26536660, 2015).
hepatocellular carcinoma (64 papers, 2010 to 2026). A malignant tumor that arises from hepatocytes. "The expression of acyl-CoA synthetase 4 (ACSL4), an enzyme working in AA metabolism, has been shown to be associated with aggressiveness of several types of cancer such as colon and hepatocellular carcinoma." (PMID 26536660, 2015). "In recent years, ACSL4 has gained increasing attention for its central role in various liver diseases, including metabolic dysfunction-associated steatotic liver disease, liver fibrosis, hepatocellular carcinoma, and ferroptosis." (PMID 41822181, 2026). "This might bring about a common mechanism, at least in tumors known to express high amounts of ACSL4, such as breast, colon and hepatocellular carcinoma, where its high expression is associated with tumorigenesis." (PMID 21085606, 2010). "In chronic injury-dependent hepatocellular carcinoma (HCC), ACSL4 deficiency alleviates hepatocyte death and proliferation, thereby suppressing HCC development by mitigating liver injury and fibrosis." (PMID 40395328, 2025). "A study has reported that miR-338-3p affects lipid peroxidation in hepatocellular carcinoma cells by regulating ACSL4 (a key enzyme of ferroptosis), indicating its potential interaction with the ferroptosis pathway." (PMID 40652291, 2025). "In summary, ACSL4-dependent ferroptosis occurs both in tumors with high ACSL4 expression (e.g., sorafenib-treated hepatocellular carcinoma) and in pathological processes like IRI affecting other tissues (e.g., transplantation)." (PMID 40932861, 2025). "In hepatocellular carcinoma, ACSL4 upregulates the main lipogenic regulator SREBP1 through c-Myc, leading to the accumulation of intracellular triglycerides, cholesterol and lipid droplets, thereby promoting malignant tumor progression." (PMID 40050614, 2025). "It has also been found that ACSL4 can affect the growth of liver tumor cells, and inhibition of ACSL4 expression can induce apoptosis of tumor cells, thereby inhibiting the development of hepatocellular carcinoma." (PMID 40148434, 2025). "For instance, miR-211-5p suppresses hepatocellular carcinoma progression by negatively regulating acyl-CoA long-chain family member 4 (ACSL4)." (PMID 40427372, 2025). "In MASH, the overexpression of ACSL4 leads to enhanced steatosis by inhibiting FAO, whereas elevated ACSL4 levels in hepatomas contribute to heightened lipogenesis by indirectly boosting SREBP1 activity." (PMID 38921460, 2024). "Meanwhile, ACSL4 appears to be abnormally expressed in a variety of clinical cancers, and ACSL4 overexpression in hepatocellular carcinoma is often predictive of poor prognosis related to HCC patients." (PMID 39311951, 2024). "The results of Western Blot showed that curcumin decreased the expression of ferroptosis-related proteins SLC7A11, GSS, GPX4, and FTH1, as well as increased the expression levels of PTGS2 and ACSL4 in hepatocellular carcinoma tissues." (PMID 39311951, 2024). "In conclusion, our study reveals a new mechanism of curcumin against hepatocellular carcinoma and identifies the core target of curcumin-mediated ferroptosis, ACSL4, which provides a broader scientific explanation for the clinical application of curcumin." (PMID 39311951, 2024). "MiR-205 (or Triacsin C, an inhibitor of ACSL4) suppressed HBx’s ability to raise cellular cholesterol levels (a metabolite of ACSL4) in hepatoma cells." (PMID 37710249, 2023). "For example, ETS1 promotes resistance to sorafenib in hepatocellular carcinoma by regulating ferroptosis via the miR-23a-3p/ACSL4 axis." (PMID 37490064, 2023). "miR-205 inhibits the expression of ACSL4 by targeting its 3′-UTR, and anti-miR-205 can accelerate lipogenesis through regulating ACSL4 in hepatoma cells." (PMID 35186915, 2022). "Recent studies have shown that ACSL4 also increased GLUT1-mediated O-Glcnacylation promotes hepatocellular carcinoma cell growth and survival." (PMID 35126480, 2022).
hepatocellular carcinoma (continued). "Recent study mentioned that ACSL4 regulates the de novo lipogenesis in hepatocellular carcinoma cells via stimulating production of intracellular cholesterols, triglycerides, and lipid droplets." (PMID 35368896, 2022). "It was found that long-chain acyl-CoA synthase 4 (ACSL4) is required for de novo synthesis of FA in hepatoma cells." (PMID 35743814, 2022). "Cell experiments found the expression of ACSL4 protein was negatively related with half maximal inhibitory concentration (IC50) values of sorafenib in hepatoma cell line." (PMID 35910359, 2022). "This miRNA was also reported to directly downregulate another isoform of ACSL, ACSL4, also in hepatoma cells leading in this case to hepatic cholesterol accumulation." (PMID 33050166, 2020). "Acyl-CoA ligase 4 (ACSL4) has been reported to be overexpressed in hepatocellular carcinoma (HCC) and to enhance cell proliferation." (PMID 32357142, 2020). "ACSL4, which mainly esterifies arachidonic acid into arachidonoyl-CoA, is increased in breast, colon and hepatocellular carcinoma." (PMID 27478411, 2016). "In addition, IFN-γ was found to trigger ferroptosis in hepatocellular carcinoma by activating the STAT1/IRF1/ACSL4 axis." (PMID 40140647, 2025). "Furthermore, higher proliferation rates, migration capacity, and colony formation have been observed upon ACSL4 overexpression in hepatocellular carcinoma and BC." (PMID 39174500, 2024). "This suggests that ACSL4 may be the core target of curcumin-mediated ferroptosis in hepatocellular carcinoma cells." (PMID 39311951, 2024). "Based on the high expression of ACSL4 in hepatocellular carcinoma, this implies that ACSL4 may be a key gene for ferroptosis resistance in hepatocellular carcinoma." (PMID 39311951, 2024). "Besides, ACSL4 also be found upregulated in hepatocellular carcinoma (HCC) and colon cancer, which is related to increased aggressiveness and poor prognosis." (PMID 37193981, 2023). "However, another recent study found the opposite effect of CREB on ferroptosis, revealing that CREB regulates acyl-CoA synthetase long-chain family member 4 (ACSL4) expression in hepatoma to promote ferroptosis and induce hepatotoxicity." (PMID 37121999, 2023). "The newly identified HK2‐acyl‐CoA synthetase long chain family member 4 (ACSL4)‐fatty acid β‐oxidation axis is an ideal therapeutic target for hepatocellular carcinoma (HCC), and GalNac‐conjugated siHK2 opens an avenue to develop a novel strategy of precision therapy for the treatment of HCC." (PMID 35603967, 2022). "For example, ACSL4 is a predictive biomarker of sorafenib sensitivity in hepatocellular carcinoma." (PMID 34531924, 2021). "There is consensus, however, regarding the involvement of the inhibition of ferroptosis in sorafenib resistance in the treatment of hepatocellular carcinoma with a recognised role for ACSL4 (acyl-CoA synthetase long-chain family member 4), a known mediator of ferroptosis." (PMID 34942967, 2021). "The expression and subcellular localisations of the ACSL3 and ACSL4 isoforms in hepatocellular carcinoma (HCC), cholangiocarcinoma (CCA) and hepatic metastases were assessed by immunohistochemical analyses of multiple tumour tissue arrays and by subcellular fractionation of cultured HepG2 cells." (PMID 32286604, 2020). "Similarly, ACSL4 knockdown inhibited growth rates of the human hepatocellular carcinoma cell line Hep3B." (PMID 25866768, 2015). "But surprisingly, the high expression of ACSL4 in HCC implies that hepatocellular carcinoma is highly sensitive to ferroptosis, and thus inducing hepatocellular carcinoma cells to target ferroptosis is a new direction for precision tumor therapy." (PMID 39311951, 2024).
hepatocellular carcinoma (continued). "Proteomics analysis revealed that miR-23a-3p inhibitors could prevent ACSL4 overexpression and reduce sorafenib-induced lipid peroxidation and cellular iron accumulation, suggesting that miR-23a-3p can affect ferroptosis by regulating ACSL4 to affect sorafenib resistance in hepatocellular carcinoma." (PMID 38590315, 2024). "The intricate relationship between bile acid (BA) metabolism, M2 macrophage polarization, and hepatitis B virus‐hepatocellular carcinoma (HBV‐HCC) necessitates a thorough investigation of ACSL4's (acyl‐CoA synthetase long‐chain family member 4) role." (PMID 39268355, 2024). "For example, ACSL4 promotes hepatocellular carcinoma (HCC) cell proliferation and metastasis via lipogenesis and LDs accumulation." (PMID 38078907, 2023). "In addition, the expression of long-chain acyl CoA synthase long chain family member 3 (ACSL3) and ACSL4 was dramatically elevated in hepatoma cells, and ACSL4 was involved in erastin-induced ferroptosis via 5-hydroxyeicosatetraenoic acid-mediated lipotoxicity." (PMID 34970553, 2021). "For example, ACSL4 was shown to facilitate hepatocellular carcinoma (HCC) development and modulate aberrant lipid metabolism via the c-MYC/SREBP1 pathway." (PMID 34868963, 2021). "In hepatocellular carcinoma (HCC), tumor cells exhibit increased expression of ACSL4 and transferrin receptor 1 (TfR1), as well as decreased GPX4 activity." (PMID 40733290, 2025). "In hepatocellular carcinoma (HCC), ACSL3 and ACSL4 have been extensively studied, with several studies indicating differential expression of these enzymes in normal liver tissue, metastatic liver lesions, and HCC tissues." (PMID 41288931, 2025). "On one hand, there are some studies supporting our outcomes, as higher ACSL4 expression has been related to lower OS, DFS, and advanced stages of hepatocellular carcinoma." (PMID 39174500, 2024). "In hepatocellular carcinoma (HCC), miR-23a-3b is considered as a prominent miRNA, and ACSL4 is found to be a target gene in Sorafenib-resistant cells in HCC." (PMID 37240889, 2023). "In addition to its involvement in tumor progression, ACSL4 serves as a biomarker for sorafenib in the treatment of hepatocellular carcinoma (HCC)." (PMID 36497375, 2022). "The acyl-CoA synthetase 4 (ACSL4), which esterify mainly arachidonic acid (AA) into acyl-CoA, is increased in breast, colon and hepatocellular carcinoma." (PMID 22808264, 2012). "MiR-23a-3p, overexpressed among sorafenib non-responders, targets ACSL4 directly and leads to sorafenib resistance, while miR-23a-3p inhibition restores ACSL4 expression and triggers ferroptosis in hepatocellular carcinoma treated with sorafenib." (PMID 39935430, 2025). "Furthermore, ACSL4 expression was shown to be elevated in hepatocellular carcinoma (HCC) compared to normal liver tissue, suggesting that ferroptotic cell death may play a role in HCC formation." (PMID 35963845, 2022). "ACSL4, GNMT, IFI27, and miR122 are known or expected to play a key role in the clinical courses of HCV-mediated liver diseases by regulating HCV replication and thereby hepatocellular carcinoma." (PMID 30138348, 2018). "Atractylodin was found to induce ferroptosis in hepatocellular carcinoma (HCC) cells by suppressing the expression of GPX4 and activating the ACSL4 and TFR1 proteins." (PMID 37833746, 2023). "However, it is undeniable that the high expression of ACSL4 in ER negative breast cancer, hepatocellular carcinoma, colorectal cancer, and prostate cancer can also be related with tumor cell proliferation, migration, and invasion." (PMID 35910359, 2022). "Furthermore, the acyl-CoA synthetase long chain family member 4 (ACSL4)-mediated ferroptosis showed a tumor-promoting role in the progression of hepatocellular carcinoma (HCC) from liver injury and a tumor-suppressing role in HCC treatment." (PMID 36999078, 2023).
hepatocellular carcinoma (continued). "First, among ACSL family members, AA treatment markedly and selectively reduced ACSL4 protein levels without affecting cellular levels of ACSL1 and ACSL5 in model hepatoma cell lines, including HepG2 and Huh7 cells as well as in primary mouse hepatocytes." (PMID 24879802, 2014).